FLI1 (Fli-1 proto-oncogene, ETS transcription factor)
Diseases named in the same sentence as FLI1 in open-access papers (continued):
Sharing a sentence is not in itself a finding about the gene and the disease.
erythroleukemia (23 papers, 2012 to 2025). Acute erythroid leukemia characterised by the presence of at least 50% erythroid precursors and at least 20% myeloblasts in the bone marrow. "Activation of Fli-1 was subsequently confirmed to underlie induction of erythroleukemias by this virus." (PMID 30741932, 2019). "In addition to erythroleukemia, the aberrantly deregulated FLI1 is also associated with other hematological malignancies, including pre-T cell lymphoblastic lymphoma, acute myeloid leukemia, and B cell lymphomas." (PMID 30537986, 2018). "Indeed, most of these clonal erythroleukemia are associated with one of three recurrent proviral insertions leading to spi-1, fli-1 or fli-3 genes deregulated expression." (PMID 23056458, 2012). "This study revealed that the DIM-derivative molecule, L1, induced ER stress-mediated apoptosis and suppressed cell growth by inhibiting the FLI1/AKT pathway in erythroleukemia HEL cells." (PMID 40822462, 2025). "FLI1, a transcription factor (TF), is involved in the development of the hematopoietic system, and its overexpression leads to the progression of erythroleukemia." (PMID 40822462, 2025). "UBASH3B and UBASH3A are found to act as an oncogene and tumor suppressor, respectively, and their combined effect determines erythroleukemia progression downstream of FLI1." (PMID 38461240, 2024). "The ETS transcription factor Fli-1 was first identified as a target of retroviral insertional activation in erythroleukemia induced by the Friend virus." (PMID 38461240, 2024). "UBASH3B was found to be a direct target of FLI1, and its activation promotes erythroleukemia growth." (PMID 38461240, 2024). "FLI1 is shown in this study to promote erythroleukemia progression by inhibiting UBASH3A and expression and inducing UBASH3B expression." (PMID 38461240, 2024). "FLI1 promotes erythroleukemia progression in part by modulating expression of the oncogenic UBASH3B and tumor suppressor UBASH3A." (PMID 38461240, 2024). "Transcription factor Friend Leukemia Integration 1 (Fli-1) was originally discovered as an activated oncogene in erythroleukemias induced by Friend Murine Leukemia Virus (F-MuLV)." (PMID 39769192, 2024). "The FLI1 gene, encoding for another ETS transcription factor, was also first studied in erythroleukemia virus models, and its overexpression reduces GATA1 expression and impairs erythroid differentiation." (PMID 38892446, 2024). "A recent study has shown that mouse Fli1 promotes chromatin looping between the Meis1 enhancers and promotor in murine erythroleukemia cells." (PMID 35624144, 2022). "Fli-1 was first identified as the main integration site of the Friend helper virus (F-MuLV), which triggers erythroleukemia in mice." (PMID 33733070, 2021). "Since FLI1 activation was frequently detected in erythroleukemias, it is therefore possible that this TF acts as an oncogene in erythroleukemias, but functions as a tumor suppressor gene in megakaryocytic leukemias." (PMID 33717090, 2021). "A661 and A665 induced differentiation and apoptosis and attenuated the growth of B-cell lymphomas expressing high levels of Fli-1 in vitro, and erythroleukemia in a preclinical model in vivo." (PMID 30741932, 2019). "We identified two chemically related diterpenoid-like compounds that suppress Fli-1 transcriptional activity and its downstream targets, leading to inhibition of B cell lymphoma in vitro and erythroleukemia in a preclinical mouse model." (PMID 30741932, 2019). "Among the ETS family members, Friend leukemia virus integration 1 (FLI1) was first identified as a proto-oncogene activated by proviral integration in F-MuLV-induced erythroleukemias." (PMID 30537986, 2018). "As shown here and in other studies, Fli-1 expression is high in some erythroleukemia cell lines (HEL, CB7), but negligible in others (K562, KH16)." (PMID 28052010, 2017).
erythroleukemia (continued). "High-levels of VEGF, which plays a critical role in tumor initiation, have also been detected in the tumor microenvironments of Fli-1-overexpressing erythroleukemias." (PMID 28418872, 2017). "In this case, Fli-1 inactivation in high-expressing AML cells should have therapeutic benefit as we showed for erythroleukemia." (PMID 28052010, 2017). "As the majority of splenic cells represent erythroleukemia in these mice, the results suggest that over-activation of Fli-1 or activation of the PKC-MAPK-Fli-1 axis by A75 suppress leukemogenesis at least in part by inducing EMD." (PMID 28052010, 2017). "Anti-FLI-1 compounds demonstrate strong anti-leukemic activity in a mouse erythroleukemia model that over-expresses FLI-1, making it possible to target FLI-1 as a treatment strategy." (PMID 27304058, 2016). "FLI1, an Ets family member of transcription factors, was originally identified as a proto-oncogene for retroviral integration of Friend virus-induced erythroleukemias." (PMID 26156017, 2015). "Anti-Fli-1 compounds had been discovered and demonstrated strong anti-leukemic activity in a mouse erythroleukemia model that overexpresses Fli-1, making it possible for targeting Fli-1 as a potent treatment strategy." (PMID 24923303, 2014). "Fli1 is highly expressed in endothelial and hematopoietic cells and was originally identified as a common integration site in retroviral-induced murine erythroleukemias." (PMID 25423036, 2014). "Moreover, FLI1 is overexpressed in the erythroleukemia cell lines, which leads to increased cell proliferation partly through the activity of the AKT pathway." (PMID 40822462, 2025). "Moreover, engineering mice with an inducible expression of the fusion EWS/FLI-1 resulted in the rapid development of erythroleukemia expressing GATA1." (PMID 38892446, 2024). "Induction of erythroleukemia is mediated through retroviral insertional activation of fli-1." (PMID 39769192, 2024). "The transcription factor FLI-1 suppresses the transcription of SHIP1 in erythroleukemia." (PMID 37443832, 2023). "For 20 years, Fli1 was viewed as a member of the ETS transcription factor family originally identified in erythroleukemia induced by the Friend Murine leukemia virus, but recent evidence indicates that Fli1 is a master of transcription factor which promotes vascular morphogenesis and angiogenesis." (PMID 35328757, 2022). "In addition to bringing new insights concerning Fli-1 contributions to cancer, our data identify three new enhancers of Meis1 in erythroleukemia." (PMID 33733070, 2021). "Moreover, these inhibitors blocked leukemogenesis in a mouse model of erythroleukemia, in which Fli-1 is the driver of tumor initiation." (PMID 30741932, 2019). "However, we did show here that megakaryocytic specific gene expression can be induced following Fli-1 transduction in erythroleukemia cells, and can be further elevated by treatment with PKCAs." (PMID 28052010, 2017). "This Fli-1 mediated restriction phenomenon is not limited to erythroleukemias and may also apply to other cancer types." (PMID 28052010, 2017). "Studies have reported that DNMT1 gene expression was controlled via transcription factor Fli-1 in erythroleukemia cells, that DNMT1 expression was increased through the JAK-STAT pathway in malignant T lymphocytes, and that AKT activity inhibited DNMT1 degradation in multiple cell lines." (PMID 24675762, 2014). "Such highly recurrent activation of one of these two transcription factors belonging to the same ETS family led us to hypothesize that Spi-1 and Fli-1 could contribute to erythroleukemia through common target genes deregulation." (PMID 23056458, 2012). "Therefore, FLI1 is considered a specific and important target for erythroleukemia treatment." (PMID 40822462, 2025). "This study evaluates the anti-erythroleukemia activities of the DIM derivative L1 in vitro and revealed that L1 induced ER stress-mediated apoptosis and mediated the FLI1/AKT pathway in HEL cells." (PMID 40822462, 2025).
erythroleukemia (continued). "The Friend Leukemia virus integration-1 (Fli-1), a member of ETS gene family, is activated by retroviral insertional mutagenesis in F-MuLV-induced erythroleukemias." (PMID 28052010, 2017). "Since FLI1 knockdown or overexpressing cells exhibit increased or decreased expression of the AP1 genes, respectively, we propose a tumor suppressor role for AP1 in erythroleukemia." (PMID 38461240, 2024). "FLI1 protein is expressed in erythroleukemia cell lines CB7, CB3, HEL, DP17-17, and HB2.22, but absent in K562 and KH16." (PMID 33717090, 2021).
acute myeloid leukemia (21 papers, 2008 to 2026). Acute myeloid leukemia (AML) is a group of neoplasms arising from precursor cells committed to the myeloid cell-line differentiation. "FLI1 is essential for normal hematopoietic development and has been implicated in various hematological disorders, including acute myeloid leukemia (AML), myelodysplastic syndrome (MDS) (Sullivan, Palmer, and Botero, 2022), and Ewing’s sarcoma." (PMID 38846805, 2024). "For example, both high and low levels of Fli-1 were found to be associated with poor survival of human acute myelogenous leukemia (AML)." (PMID 28052010, 2017). "FLI-1 is a predictor of poor prognosis in breast and endometrial cancers and acute myeloid leukemia." (PMID 38280044, 2024). "In acute myeloid leukemia, FLI-1 suppression inhibits cell growth and induces cell death, indicating that FLI-1 plays a crucial role in the survival and maintenance of leukemic cells." (PMID 38280044, 2024). "A similar role has been described for Fli-1 in AML-ETO acute myeloid leukemia cells where the AML-ETO oncoprotein is recruited to pre-occupied Fli-1 bound regions." (PMID 33733070, 2021). "They demonstrated that many recurrent chromosomal translocations, of PML/RARα observed in Acute Promyelocytic Leukemia (APL), MLL/AF9 in Acute Myeloid Leukemia (AML), EWSR1/FLI1 in Ewing Sarcoma and EML4/ALK1 associated with lung cancer could form f-circRNAs." (PMID 30018188, 2018). "In Acute Myeloid Leukemia (AML) and whole blood cells, the expression of FLI1 was significantly correlated with the level of UBASH3B." (PMID 38461240, 2024). "We compared these changes to those induced by FLI1 and ERG1 alone as well as to those induced by an isoform of FUS-ERG associated with acute myeloid leukemia (AML) but not ESFT." (PMID 18648544, 2008). "Similarly, in acute myeloid leukemia, BRD4 has been shown to co-localize and synergistically interact with hematopoietic TFs (including PU.1, FLI1, ERG, C/EBPα, C/EBPβ, and MYB) combined with lysine acetyltransferase p300/CBP to support specific transcriptional circuits in this disease." (PMID 37446009, 2023). "Erythroid acute myeloid leukemia (AML) cell line OCI-M2 expresses a particular oncogenic network: IRF6, in concert with ETV2 and HEY1, aberrantly activates NKL homeobox gene NKX2-4, which in turn represses megakaryocytic lineage factor FLI1." (PMID 41892358, 2026). "In addition, chromosomal translocations between the EWSR1 and FLI1 loci and between the AML1 (also known as RUNX1) and ETO (also known as RUNX1T1) loci, which are involved in Ewing’s sarcoma and acute myeloid leukemia (AML), respectively, have been generated by CRISPR in human cell lines." (PMID 26060510, 2015).
lupus (19 papers, 2010 to 2025). "Specifically, Fli-1 exerts control over inflammatory processes, influencing key effectors and signaling pathways associated with conditions such as systemic lupus erythematosus, scleroderma, cancer, and sepsis." (PMID 40305194, 2025). "FLI1 is a transcription factor, is an important regulator of several chemokines and cytokines, and has been implicated in nephritis in lupus mouse models." (PMID 40998523, 2025). "Elevated FLI1 levels in peripheral blood mononuclear cells (PBMCs) have been linked to lupus severity." (PMID 39140108, 2024). "The potential of FLI1 as a therapeutic target in human autoimmune diseases such as systemic sclerosis and systemic lupus erythematosus has been proposed, and the loss of FLI1 in CD8+ T cells enhances immunity to tumors has also been reported." (PMID 38448802, 2024). "Sustained Fli1 downregulation is associated with the development of systemic sclerosis, while overexpression of the FLI1 gene is a well-acknowledged event in systemic lupus erythematosus." (PMID 36768203, 2023). "In particular, Fli-1 is implicated in the development of lupus prone mouse strains, and elevated expression of Fli-1 is associated with active human lupus nephritis." (PMID 37790939, 2023). "ETS1 and FLI1, susceptibility genes associated with systemic lupus erythematosus, were differentially expressed in CD4+ and CD8+ effector cells in G1 and G3." (PMID 36703979, 2022). "Transcription factor Fli-1 regulates G-CSF production to control neutrophil infiltration into the kidneys, causing kidney inflammation in lupus." (PMID 30545086, 2018). "The transcription factor Fli1 is implicated in the pathogenesis of systemic lupus erythematosus (SLE)." (PMID 21087477, 2010). "Different from lupus, Fli-1 has an inverse correlation with the production of inflammatory mediators in skin." (PMID 40305194, 2025). "Fli-1′s regulation of the IL-1β and IL-18 genes in lupus mice was further confirmed in the lung pericytes of Cecal ligation and puncture (CLP)-induced sepsis models." (PMID 40305194, 2025). "Fli-1/inflammatory mediator axis has been shown to be involved in the pathogenesis of various inflammatory diseases including systemic lupus erythematosus (SLE), systemic sclerosis (SSc), sepsis, and cancer." (PMID 40305194, 2025). "The abnormal expression of Fli-1 has been associated with the pathogenesis of SLE in both patients and a murine model of lupus." (PMID 38256157, 2024). "Previously, elevated FLI1 levels in PBMCs were observed in lupus patients and were related to disease severity." (PMID 39140108, 2024). "The overexpression of FLI-1 in healthy mice leads to lupus-like lesions, while low FLI-1 expression significantly reduces pathological changes in the kidneys in mouse models of lupus, thereby prolonging their survival." (PMID 39107790, 2024). "In lupus, aberrant Fli-1 expression and activity have been reported in immune cells, including T cells and B cells." (PMID 38256157, 2024). "Reduced Fli-1 expression in lupus mice leads to decreased renal Cxcl10 mRNA levels and renal infiltrating CXCR3+ T cells that parallels reduced renal inflammatory cell infiltration and renal damage." (PMID 37790939, 2023). "FLI1 haplodeficiency in MRL/lpr lupus-prone mice was shown to decrease the pathogenicity of T cells by reducing TCR-specific activation and IL-4 production in part through the modulation of glycosphingolipid metabolism." (PMID 37554724, 2023). "Together, these results support a role for FLI-1 in modulating the CXCL10-CXCR3 axis by directly or indirectly regulating the expression of both genes to impact lupus disease development." (PMID 37790939, 2023). "Genetically reducing the expression of Fli-1 in two lupus mouse models significantly reduced renal damage with profoundly decreased infiltrating inflammatory cells, and prolonged survival." (PMID 37790939, 2023).
lupus (continued). "Reduced expression of Fli-1 in two lupus mouse strains significantly attenuated renal disease evidenced by decreased infiltrating inflammatory cells and prolonged survival." (PMID 37790939, 2023). "Our present study reports for the first time that FLI-1 impacts CXCL10 protein expression in kidneys of lupus mice and inflammatory cells." (PMID 37790939, 2023). "Deacetylation at aa380 decreases Fli-1 driven activation of the G-CSF promoter to decrease inflammatory cytokine secretion in lupus prone mice." (PMID 30545086, 2018). "Together, our results suggest reducing FLI1 in lupus decreases the pathogenicity of T cells by decreasing TCR-specific activation and IL-4 production in part through the modulation of glycosphingolipid metabolism." (PMID 24040398, 2013). "Global overexpression of FLI1 in otherwise healthy mice resulted in development of a lupus-like kidney disease and expansion of autoreactive T cells, suggesting a role for FLI1 in lupus disease development/progression." (PMID 24040398, 2013). "In this study we analyze the effects of reducing FLI1 in the MRL/lpr lupus prone model on T cell function." (PMID 24040398, 2013). "The mechanism(s) and the cell types involved in the protective effect of reducing FLI1 levels in lupus mice are not completely understood." (PMID 24040398, 2013). "To examine specific functional effects of Fli1+/- compared to Fli1+/+ lupus T cells, we performed an adoptive transfer experiment using Rag1-/- mice as recipients." (PMID 24040398, 2013). "Delineating the extrinsic versus intrinsic effects of altering FLI1 levels in T cells and the contribution of other cell types to the protective effect of reducing FLI1 levels in lupus are ongoing." (PMID 24040398, 2013). "These novel observations provide important mechanistic insight into the impact of FLI1 levels on lupus T cell function and progression of disease." (PMID 24040398, 2013). "Increasing evidence suggests that dysregulation of the transcription factor Fli1 contributes to the pathogenesis of lupus." (PMID 21087477, 2010). "Fli1 is over-expressed in several lupus mouse models including T cells of NZB/NZW f1 mice and spleen of MRL/lpr mice." (PMID 21087477, 2010). "Over-expression of Fli1 in peripheral blood mononuclear cells (PBMCs) in lupus patients is correlated with disease activity." (PMID 21087477, 2010). "Based on results in lupus mouse models in which reducing Fli1 levels resulted in decreased autoantibody levels, we expected to observe an association of the Fli1 microsatellite with autoantibody production." (PMID 21087477, 2010). "In lupus mouse models in which Fli1 levels were reduced globally or specifically in hematopoietic cells, nephritis was improved." (PMID 21087477, 2010). "Together these studies demonstrated that modulating Fli1 levels plays an important role in the progression of lupus." (PMID 21087477, 2010). "Therefore, Fli-1 affects lupus development by directly regulating the expression of inflammatory mediators and the migration of inflammatory cells." (PMID 40305194, 2025). "Thus, renal CXCL9 and CXCL10 are decreased at the transcript and protein levels in lupus prone MRL/lpr Fli-1+/−- mice and suggests FLI-1 modulates CXCL10, CXCL9 expression in the kidneys during lupus nephritis." (PMID 37790939, 2023). "Together, these results demonstrate a novel role for FLI-1 in modulating the CXCL10-CXCR3 inflammatory axis in lupus that may involve direct and indirect mechanisms of transcriptional regulation." (PMID 37790939, 2023). "FLI-1 impacts glomerulonephritis development by regulating inflammatory chemokines in endothelial cells, as well as inflammatory cell infiltration in the kidneys during lupus." (PMID 37790939, 2023). "Signaling pathways or drugs that reduce FLI-1 expression may offer novel approaches to lupus treatment." (PMID 37790939, 2023). "Since reducing FLI-1 decreases expression of CXCL10, FLI-1 may be an alternative drug target for lupus, an ongoing focus in our lab." (PMID 37790939, 2023).